PAFAH2 (platelet activating factor acetylhydrolase 2)
Description:
Catalyzes the hydrolyze of the acetyl group at the sn-2 position of platelet-activating factor (PAF) and its analogs, leading to their inactivation. Hydrolyzes propionyl and butyroyl moieties approximately half as effectively as PAF (By similarity). Also catalyzes transacetylation of the acetyl group from platelet-activating factor (PAF) to lysoplasmalogen and to sphingosine, producing plasmalogen analogs of PAF and N-acetylsphingosine (C2-ceramide) respectively. Has a marked selectivity for phospholipids with short acyl chains at the sn-2 position (By similarity).
Synonyms: hSD-PLA2
Tractability: PROTAC: ubiquitination databases record sites on it; its protein half-life has been measured.
Chemical probes: ML225
Gene: Protein-coding gene on chromosome 1 (25,959,767 to 25,999,206, reverse strand). Ensembl gene ENSG00000158006.
Subcellular location: Cytoplasm; Membrane; Endoplasmic reticulum membrane
Pathways (Reactome):
Hemostasis: Platelet homeostasis
Gene Ontology:
Molecular function: 1-alkyl-2-acetylglycerophosphocholine esterase activity; phospholipid binding; platelet-activating factor acetyltransferase activity
Biological process: blood coagulation; lipid metabolic process
Cellular component: cytoplasm; endoplasmic reticulum membrane; membrane
Genetic constraint (gnomAD): Loss-of-function variants: 35 observed, 41.5 expected, observed/expected ratio (o/e) 0.84, 90% interval 0.64 to 1.12. The upper end of that interval is the gene's LOEUF score, 1.12, which puts it in group 4 of 6, group 1 being the genes least tolerant of losing a copy. Missense variants: 470 observed, 495.47 expected, observed/expected ratio (o/e) 0.95, 90% interval 0.88 to 1.02. Synonymous variants: 180 observed, 179.16 expected, observed/expected ratio (o/e) 1, 90% interval 0.89 to 1.14.
Homologues: Orthologues: chimpanzee PAFAH2 (99% identical), dog PAFAH2 (89% identical), rabbit PAFAH2 (87% identical), guinea pig PAFAH2 (86% identical), macaque PAFAH2 (86% identical), pig PAFAH2 (83% identical), mouse Pafah2 (78% identical), rat Pafah2 (78% identical), tropical clawed frog pafah2 (47% identical), Caenorhabditis elegans paf-1 (33% identical), Caenorhabditis elegans paf-2 (32% identical). Paralogues in human: PLA2G7 (42% identical).
Diseases named in the same sentence as PAFAH2 in open-access papers:
PAFAH2 is named in the same sentence as 18 diseases in open-access papers, as found by Europe PMC text mining. Sharing a sentence is not in itself a finding about the gene and the disease. The quoted sentences say what the papers report.
endothelial dysfunction (2 papers, 2018 to 2020). In vascular diseases, endothelial dysfunction is a systemic pathological state of the endothelium (the inner lining of blood vessels) and can be broadly defined as an imbalance between vasodilating and vasoconstricting substances produced by (or acting on) the endothelium. "Moreover, we also showed that inhibition of Tr-OxPLs production by PAFAH2 rescues PM-induced endothelial cell barrier disruption, suggesting a critical role of PM-ROS-TrOxPLs signaling axis during endothelial dysfunction caused by PM exposure." (PMID 30419037, 2018).
pulmonary arterial hypertension (2 papers, 2022). Pulmonary arterial hypertension (PAH) is a group of diseases characterized by mean pulmonary artery pressure >20 mmHg and elevated pulmonary arterial resistance leading to right heart failure. "Furthermore, the whole-exome sequencing of patients with pulmonary arterial hypertension identifies two candidate pathogenic variants of the PAFAH2 gene." (PMID 35833146, 2022).
Sepsis (2 papers, 2021 to 2023). Sepsis is defined as life-threatening organ dysfunction caused by a dysregulated host response to infection. "In the present study, we identified 5 lipid metabolism-related hub genes (MAPK14, EPHX2, BMX, FCER1A, and PAFAH2) that have the possibility of diagnostic and therapeutic in patients with sepsis by machine learning analysis." (PMID 37180171, 2023). "Therefore, PAFAH2, as a hub gene, may play a crucial role in lipid metabolism during sepsis and can predict the outcome of sepsis patients." (PMID 37180171, 2023).
Cerebral ischemia (1 paper, 2013). Restriction of arterial blood supply to the brain associated with insufficient oxygenation to support the metabolic requirements of the tissue. "Moreover, studies using a mouse model of focal cerebral ischemia showed that PAFAH2 exerts strong neuroprotective effects against ischemic injury in the CNS by protecting neurons against oxidative stress." (PMID 23977941, 2013).
COVID-19 (1 paper, 2025). A disease caused by infection with severe acute respiratory syndrome coronavirus 2. "Five genes, including PAFAH2, LINC02915, CLSPN, EIF4G1 and IFI27, were predictors of both COVID-19 and RSV-LRTI hospitalization." (PMID 41279033, 2025).
fibrosis (1 paper, 2022). the formation of excess fibrous connective tissue in an organ or tissue in a reparative or reactive process. "19,20-EpDPE administrations significantly improved PH by suppressing advanced pulmonary vascular remodeling including perivascular fibrosis both in the WT mice and in the Pafah2 KO mice, but DHA or ω-6 epoxide, 14,15-EET, did not exhibit the beneficial effects." (PMID 35641514, 2022).
heart failure (1 paper, 2022). Inability of the heart to pump blood at an adequate rate to meet tissue metabolic requirements. "Furthermore, Pafah2 KO mice with hypoxic PH exhibited advanced right heart failure, such as increased right ventricular (RV) hypertrophy and higher mRNA levels of Nppa, a heart failure marker, in the RV, resulting in a high mortality rate of nearly 80% in 100 days after hypoxic exposure." (PMID 35641514, 2022).
hepatocellular carcinoma (1 paper, 2022). A malignant tumor that arises from hepatocytes. "In humans, PAFAH2 has been linked to intracranial aneurysms while STMN1 has recently been proposed as a biomarker for hepatocellular carcinoma prognosis." (PMID 35782544, 2022).
Hypercalcemia (1 paper, 2022). An abnormally increased calcium concentration in the blood. "The hypercalcemia GWAS produced a suggestive association (P = 6.81 × 10−7 in LMM, P = 3.05 × 10−7 in FarmCPU) on chromosome C1, located in the gene PAFAH2 (Platelet Activating Factor Acetylhydrolase 2) and within LD of the gene STMN1 (Stathmin 1)." (PMID 35782544, 2022). "The second suggestive association was identified for hypercalcemia and the LD region contained the genes PAFAH2 and STMN1, neither of which have been associated with hypercalcemia previously." (PMID 35782544, 2022).
leukemia (1 paper, 2020). A malignant (clonal) hematologic disorder, involving hematopoietic stem cells and characterized by the presence of primitive or atypical myeloid or lymphoid cells in the bone marrow and the blood. "Thus, we studied the expression of ceramide synthase genes (CERS-1, -2 -4 and -5) and PAFAH2 in primary AML samples and transfected leukemia cell lines." (PMID 32161116, 2020).
prostate carcinoma (1 paper, 2017). A carcinoma that arises from epithelial cells of the prostate gland. "PC3 prostate cancer cells stably expressing FLAG-tagged PAFAH2 and ESD were pulsed with FP-Bio and processed for ADPL with an anti-FLAG antibody." (PMID 29176560, 2017).
renal carcinoma (1 paper, 2023). A carcinoma arising from the epithelium of the renal parenchyma or the renal pelvis. "Knockdown of PAFAH2 contributed to renal cancer cell proliferation and migration." (PMID 37460577, 2023).
cancer (1 paper, 2023). A tumor composed of atypical neoplastic, often pleomorphic cells that invade other tissues. "We demonstrated that in ccRCC cells, reduced PAFAH2 promotes cancer cell proliferation and migration." (PMID 37460577, 2023). "It is known that the roles of ACADSB, ACADM, HADH, PYCR1 and ITPKA have been explored in cancers, whereas PAFAH2 not12–16." (PMID 37460577, 2023). "Due to the reason that the biological roles of PAFAH2 have never been explored in cancers, therefore, the expression and role of PAFAH2 were investigated in ccRCC cells." (PMID 37460577, 2023).
tumor (1 paper, 2023). "Combined with these, PAFAH2 may act as a tumor suppressor in ccRCC." (PMID 37460577, 2023).
PAFAH2 also shares sentences with these, for which no sentence is quoted: colon cancers (1 paper); infection (1); intracranial aneurysms (1); pulmonary hypertension (1).